IL2 (interleukin 2)
Diseases named in the same sentence as IL2 in open-access papers (continued):
Sharing a sentence is not in itself a finding about the gene and the disease.
melanoma (continued). "The agents previously approved for systemic adjuvant treatment of melanoma included dacarbazine, cisplatin, vinblastine, IL-2, interferon alfa-2b and pegylated interferon, which showed inconsistent improvements in OS along with substantial toxic effects." (PMID 31762821, 2019). "Diagnostic potential and prognostic significance of cytokines in human melanoma have already been documented with the first cancer patient responding to the administration of IL-2 in 1984 and remaining disease-free for the past 29 years." (PMID 30987001, 2019). "For human CD8+ T cells isolated from the peripheral blood of healthy donors, IL-21 promotes Tscm development in vitro leading to improved immunity upon adoptive transfer into mice with melanoma compared to IL-2-stimulated CD8+ T cells." (PMID 30842774, 2019). "In fact, the hRT/IL-2c combination had a better antitumor effect on aggressively growing B16 melanoma tumors than hRT alone or hRT + free IL-2." (PMID 30808414, 2019). "Patient 9, who had progressive melanoma metastases, received only two doses of IL-2 due to IL-2-induced fluid retention." (PMID 30747243, 2019). "The enhancement of immune responsiveness induced by K35E IL-2/Fc translated into a strong anti-metastatic effect in a mouse model of experimental lung metastasis after injection of MB16F0 melanoma cells." (PMID 30692603, 2019). "When applied in a model of cancer immunotherapy, optimized mutant replicons identified here harboring the immunoregulatory cytokine interleukin-2 significantly improved treatment of murine B16F10 melanoma." (PMID 31061426, 2019). "This compound, Neo-2/15, showed enhanced activation of murine and human T and NK cells and superior therapeutic activity compared with IL-2 in murine models of melanoma and colorectal cancer." (PMID 31340613, 2019). "In comparison to wildtype replicon, mutants expressing IL-2 injected into murine B16F10 melanoma showed 5.5-fold increase in intratumoral IL-2 and 2.1-fold increase in infiltrating CD8 T cells, resulting in significantly slowed tumor growth." (PMID 31061426, 2019). "A trial using a vaccine against gp100 combined with immune-modulators (e.g., IL2) is under way for melanoma patients." (PMID 31575023, 2019). "In another context, after an initial lysis of melanoma cell lines by IL-2-activated human NK cells from healthy donors, melanoma cells acquired resistance to these IL-2-activated cells preventing cell lysis." (PMID 31547251, 2019). "Briefly, T-cells from melanoma patient PBMCs were cultured for one week in the presence of 6000IU/mL IL-2 plus ACY-1215 or ACY-241." (PMID 30728070, 2019). "In a lactate dehydrogenase (LDH) release assay performed on co-culture (T cell/melanoma cells) this result was confirmed, and a further sign of T cell activation was the restored level of IL-2 in co-culture CM in the polyphenols treated groups." (PMID 30959898, 2019). "The first immunotherapeutic to show effect against melanoma brain metastasis was high dose interleukin 2 (hdIL-2)." (PMID 32309611, 2019). "Here, we report on the results of a phase II trial of a modified TIL treatment protocol for patients with advanced melanoma, substituting low-dose, subcutaneous IL-2 for the standard high-dose intravenous administration." (PMID 30747243, 2019). "IL-2 has antitumor activity and, in humans, recombinant IL-2 immunotherapy has been used clinically for treating melanoma." (PMID 30947707, 2019). "Administration of IL-2, which supports the survival and function of tumor-reactive T cells, has been shown to benefit some patients with melanoma." (PMID 31114758, 2019). "T-cells from melanoma patient PBMCs were expanded for one week in 6000IU/mL IL-2, plus ACY-1215 or DMSO." (PMID 30728070, 2019). "Of note, IL-2 is the first cytokine approved as an effective immunotherapy in melanoma and renal cancer, due to its ability to expand T cells." (PMID 30658426, 2019).
melanoma (continued). "We set up an overnight co-culture with melanoma cells in the presence of soluble TGFβ (1.25 ng/ml) and measured IL-2 secretion in the supernatant by ELISA." (PMID 31500665, 2019). "Loxoribine has also been shown to inhibit the metastasis of B16 melanoma cells, with significantly better results when given in combination with IL2 injections." (PMID 31835892, 2019). "IL2 has been extensively studied in several tumours, including melanoma, squamous cell carcinomas of head and neck, and renal cell carcinoma, showing optimal biodistribution, dosimetry and high T/B ratio." (PMID 31091813, 2019). "The cytokine IL-2 has been approved for the treatment of metastatic renal cell carcinoma and advanced melanoma but is accompanied by severe side effects." (PMID 31681606, 2019). "More recently, better IL-2 based cell transfer therapies with effective response in melanoma have been developed." (PMID 29854806, 2018). "Next, we examined 21 early stage melanoma primary skin lesions prior to surgical resection with 99mTc-IL2 imaging for the presence of TIL and corresponding 99mTc-IL2 uptake by histologic evaluation of the surgical specimen." (PMID 30100988, 2018). "In summary, our results showed that ACT without a lymphocyte-depleting regimen and with subcutaneous low-dose IL-2 was safe in heavily pretreated advanced melanoma patients." (PMID 29750176, 2018). "PBMCs obtained before and 1 month after M-ILP were cultured with presence of peptides from common viral antigens (HCMV/EBV/influenza virus) or melanoma-associated peptides (NY-ESO-1/Melan-A/gp100), supplemented with IL-2." (PMID 30560089, 2018). "HD IL-2 was the first systemic immunotherapy approved for patients with advanced melanoma but efficacy was observed in a select number of patients." (PMID 30053905, 2018). "High-dose interleukin 2 (HD IL-2) was the first reported immunotherapy capable of mediating a long-term and complete response (CR) in patients with advanced melanoma and renal cancer." (PMID 29725606, 2018). "The U.S. food and drug administration (FDA) first approved the use of interferon and interleukin 2 (IL-2) for melanoma based on better responses compared to the use of classical chemotherapy." (PMID 29370105, 2018). "All 21 melanoma lesions had lymphocytic infiltration at histology and 15 were judged to have positive 99mTc-IL2 scan findings." (PMID 30100988, 2018). "Although TILs can readily be expanded from melanoma biopsies by the addition of high-dose IL-2 alone, expanding TILs from other solid tumours has been significantly more challenging." (PMID 30039427, 2018). "That finding served as the basis of ACT for melanoma that obtained a 34% objective response rate in 86 melanoma patients treated with TILs and high-dose IL-2." (PMID 29750176, 2018). "Our lab has previously shown that local radiation therapy (RT) combined with intratumoral (IT) immunocytokine (IC; a fusion of hu14.18 anti-GD2 mAb and IL2) can cure mice with melanoma." (PMID 30400835, 2018). "Histamine has been shown to play an important role in immune cell function, and a histamine/IL‐2 combination has been used to increase T‐cell responses in stage IV melanoma patients." (PMID 29193607, 2018). "Daily single intravenous Interleukin-2 (IL-2) infusions (pulses) have been developed to decrease toxicity while maintaining anticancer activity of this molecule against melanoma." (PMID 30400822, 2018). "Since the early 90s immuno-stimulation with interleukin-2 (IL-2) has been used to treat melanoma and renal cell carcinomas." (PMID 29872502, 2018). "A lot of researchers have reported about the imbalance of cytokines in patients with melanoma - statistically low levels of IL-2 and IFN-γ and high levels of IL-4, IL-6 and IL-10 that reflects the imbalance between Th1/Th2 immune responses." (PMID 29849947, 2018). "The use of IL-2 to stimulate an effective immune response against metastatic cancers, such as melanoma and renal cell carcinoma, dates back to the early 1980s." (PMID 30250191, 2018).
melanoma (continued). "After 2 days of co-culture of melphalan-exposed melanoma cells and PBMCs, the PBMCs were transferred to a new plate and were expanded for 2 weeks in the presence of IL-2." (PMID 30560089, 2018). "High dose (HD) IL-2 is another well-described immunotherapy that has been administered in both melanoma and renal cell carcinoma with a complete and durable response in approximately 8% of patients." (PMID 29644213, 2018). "We discovered that the combination of Teff + Tmem led to the strongest control of melanoma tumor growth, potentially due to complementary cell killing patterns and local production of IL-2 by Tmem." (PMID 29843822, 2018). "High-dose interleukin-2 (IL-2) for the treatment of melanoma: safety considerations and future direction." (PMID 30400835, 2018). "FDA approval of HD IL-2 for the treatment of patients with renal cancer and melanoma was granted in 1992 and 1998, respectively, which established immunotherapy as the newest paradigm for the treatment of cancer." (PMID 29725606, 2018). "The effects of flavonoid treatment on melanoma sensitivity towards T cells were investigated using Jurkat cell killing, cytotoxicity, cell viability, and IL-2 secretion assays." (PMID 30373602, 2018). "There is considerable evidence supporting a role for high-dose IL-2 in the treatment of patients with stage IV melanoma, and the drug has been approved since 1998." (PMID 29848375, 2018). "For instance, a combinational protocol utilizing IL-2 or GM-CSF along with hyperthermia resulted in complete eradication of tumors in melanoma-bearing mice." (PMID 30013176, 2018). "Disease control rate and 3-year overall survival, however, were as would be expected with HD IL-2 therapy alone in patients with advanced malignant melanoma." (PMID 30053905, 2018). "MDNA109-Fc is an improved interleukin-2 agent with a unique biased activation profile targeting effector versus immunosuppressive immune cells, and improved efficacy in a melanoma model." (PMID 30400822, 2018). "In fact, in a melanoma DC vaccine clinical trial with low-dose cytokines (IL-2 and IFN-gamma), Tregs were significantly increased by the fourth dose of the DC vaccine and were correlated with disease progression." (PMID 30297856, 2018). "Although, treatment of renal cell carcinoma patients with an IL-2 encoding plasmid led to a low number of responses, injection of recombinant IL-2 into melanoma metastases induced high response rates resulting in tumor regression." (PMID 30619273, 2018). "What makes the lung metastatic model so meaningful is that wild-type IL-2 is frequently used in clinical therapy to prevent tumor cells from metastasizing and to accelerate the regression of melanoma." (PMID 30250191, 2018). "From the in vitro M-ILP model it was obvious that the expansion of CD8+ T cells in PBMCs that had been co-cultured with melphalan-exposed melanoma cells was significantly enhanced by the presence of IL-2." (PMID 30560089, 2018). "HD IL2 administered as a single agent has proven to be one of the most effective regimens for metastatic renal cell carcinoma and melanoma to date." (PMID 30342473, 2018). "IL-2 is already approved by the FDA as a first-line treatment for patients with renal cell carcinoma and melanoma, although the systemic administration is associated with significant toxicity." (PMID 30619273, 2018). "From day 8 we observed that melanoma on the mice treated with wild-type IL-2 grew faster at an accelerating pace, reaching 260 mm2 on average on day 14, which was only 40 mm2 smaller than the size of the melanoma measured in the PBS group." (PMID 30250191, 2018). "In this quest, IL-2 has gained particular recognition in treating melanomas and renal cell carcinomas by augmenting the tumor-reactive CD8 T cell pool." (PMID 30619342, 2018).
melanoma (continued). "The presence of soluble CD25 (the α-chain receptor of interleukin-2; IL-2) in pre-treatment serum of melanoma patients undergoing anti-CTLA-4 mAb therapeutic regimen has been shown to be an independent indicator of OS." (PMID 30004433, 2018). "Cancer immunotherapy used to have limited applications, mainly for selected cancers like melanoma and renal cancers and involved the use of interleukin 2 (IL-2)." (PMID 29996517, 2018). "Local administration of IL2 was shown to be highly effective in controlling malignant melanoma, but remission was observed after withdrawal of IL2 therapy." (PMID 29467958, 2018). "Inhibition of IL-2 causes the accumulation of immunosuppressive substances like gangliosides, which are produced by melanoma cells and inhibit the production of IL-2 by directly damaging the molecules." (PMID 29849947, 2018). "SELECT and PROCLAIM are IL-2 patient databases with more than 40 participating sites consisting of retrospective melanoma and prospective melanoma cohorts." (PMID 29644213, 2018). "PH is extremely rare in malignant melanoma, however, most patients who developed this complication had preceding immunotherapies such as interleukin-2." (PMID 30376886, 2018). "This marked the beginning of an extended quest to identify immune-based antitumor regimens, leading to the FDA approval of adjuvant therapy in stage III melanoma with high-dose interferon in 1996 and of high-dose bolus IL-2 for advanced melanoma in 1998." (PMID 29946532, 2018). "As a result, wild type IL2 (aldesleukin, Proleukin®) has been approved as a drug for treatment of metastatic renal cell carcinoma and malignant melanoma." (PMID 29467958, 2018). "It has been shown that IL-2 and IL-15 activate NK cells and exhibit enhanced cytotoxicity against CSCs derived from melanoma and breast cancer." (PMID 28137308, 2017). "Loss of B2M was also observed previously in melanoma patients treated with ex vivo expanded CD8+ T cells and IL-2." (PMID 29121062, 2017). "Melanoma-specific CD8 αβ T cells expand to a similar degree in high dose IL-2 (300 IU/ml) or IL-15 and produce equal amounts of IFN-γ." (PMID 28239463, 2017). "In some studies, as is the case of a trial investigating the use of an anti-melanoma vaccine in conjunction with IL-2, the patients experienced autoimmune reactions such as vitiligo (7%) and autoimmune thyroiditis (25%)." (PMID 28536346, 2017). "The treatment of stage III malignant melanoma patients with TIL in combination with IL-2 has previously demonstrated promising results." (PMID 28913367, 2017). "The current immunotherapy for melanoma include cytokine agents (IL-2 and IFN-α) and antibodies against CTLA-4 and PD-1." (PMID 28567163, 2017). "The major clinically approved immunotherapies for melanoma include adjuvant treatments such as IL-2 and interferon alfa." (PMID 29276510, 2017). "We next sought to evaluate the effect of exogenous TNF on CD8+ TILs purified from human melanoma samples under basal conditions (i.e., IL-2 alone) or after autologous re-stimulation with melanoma cells for 48 h." (PMID 29273790, 2017). "Preclinical studies on a melanoma mice model showed that IL2-Fc exerts a synergetic action with different antitumor antibodies, by promoting NK Cell and CD8+ T cell activation and consolidating with the antibodies antitumor therapy." (PMID 28927416, 2017). "The administration of IL-2 as well as the adoptive transfer of IL-2-activated lymphocytes represented the first effective cancer immunotherapy for solid tumors such as melanoma." (PMID 28824651, 2017). "For example, a phase III trial investigating the use of interleukin (IL)-2 and gp100 peptide vaccination for melanoma patients demonstrated an improved overall survival (17.8 vs. 11.1 months)." (PMID 28536346, 2017).
melanoma (continued). "To provide estimates of the toxicity and efficacy of this method of administration, we conducted a retrospective analysis of response, survival and toxicity data of 243 advanced melanoma patients treated with HD IL-2 between 1992 and 2015." (PMID 28923120, 2017). "In conclusion, this pooled analysis of patients with advanced melanoma treated with HD IL-2 in the modern era adds to the available data indicating durable long-term survival in responders." (PMID 28923120, 2017). "This progress through immunotherapy builds upon earlier successes that interferon-α had in the treatment of melanoma in the adjuvant setting, as well as that of high-dose interleukin-2 in advanced melanoma." (PMID 28434398, 2017). "This is in contrast to what we found with the B16 melanoma model, but similar to our recent observations comparing IL-2 and IL-7/15 in the 4T1 mammary carcinoma model." (PMID 28146052, 2017). "Interleukin-2 (IL-2) has been FDA-approved since 1998 for advanced melanoma therapy, based on data from phase 2 studies." (PMID 29179523, 2017). "Between March 1992 and June 2015, data from 243 patients with American Joint Committee on Cancer (AJCC) stage IV melanoma who had received at least 1 cycle of HD IL-2 were aggregated." (PMID 28923120, 2017). "The addition of activated tumor-infiltrating lymphocytes (TILs) in combination with IL-2, initially studied in advanced melanoma, but now in multiple tumor types, continues to be investigated." (PMID 29254506, 2017). "Inhibition of melanogenesis by tyrosinase inhibitors sensitized melanoma cells towards cytotoxic action of chemotherapeutic agents or immunotoxic activities of IL-2 activated lymphocytes." (PMID 29045474, 2017). "Cytokine employment to melanoma treatment is currently mostly limited to IL-2 and IFNα, although attempts of application of GM-CSF encoded by oncolytic virus have been done." (PMID 29236046, 2017). "Following the approval of BRAF/MEK inhibitors and PD-1/CTLA-4 blocking antibodies starting in 2011, the use of HD IL-2 in the frontline therapy of melanoma gradually declined." (PMID 28923120, 2017). "Two other large series have studied the efficacy of HD IL-2 in patients with melanoma and renal cell carcinoma (RCC): Providence Cancer Center (314 melanoma patients) and a more recent PROCLAIMSM registry (170 melanoma patients) study." (PMID 28923120, 2017). "First cytokine therapies of melanoma were realized in the 1980s with interleukin 2 (IL-2) and interferon α (IFNα) and up to 20% of tumours showed response to such therapies." (PMID 29236046, 2017). "S4428z-equipped T-cells secreted significant amounts of IFNγ, IL2, and TNFα when cocultured with cells from the primary melanoma culture M#3 (e.g., 3,987, 343, and 1,027 pg/ml, respectively), underscoring the potential clinical relevance of our approach." (PMID 29085357, 2017). "Prior studies demonstrated that this subset, CD8+BTLA+ T cells, possess a high proliferative capacity, generate their own IL-2 and display enhanced persistence in melanoma patients after TIL ACT." (PMID 27057427, 2016). "Since this concentration of IL-2 was also used in our GMP-compliant ACT protocol for the generation of melanoma-specific T cell batches, the subsequent expansions of HPV-specific T cells from patient TDLN were performed with 150 U/ml of IL-2." (PMID 27619514, 2016). "Immune complexes consisting of low-dose IL-2 and the S4B6 clone of the anti-IL-2 antibody was found to inhibit metastasis of melanoma and leukemia in a mouse model by inducing the expansion of CD8+ T and NK cell populations." (PMID 26772545, 2016). "Baseline characteristics of melanoma and renal cell carcinoma patients undergoing high dose interleukin-2 treatment in United States from 2003 to 2011." (PMID 26799322, 2016). "Preliminary retrospective analysis in patients with advanced malignant melanoma suggests that HD IL-2 is a safe treatment option for patients who have had progressive disease after ipilimumab." (PMID 27660706, 2016).